IL6 (interleukin 6)
Diseases named in the same sentence as IL6 in open-access papers (continued):
Sharing a sentence is not in itself a finding about the gene and the disease.
Sepsis (continued). "The overall pooled AUROC is 0.701 (95% CI: 0.660–0.742), indicating that the ability of baseline IL-6 levels to predict 28-day mortality in sepsis patients is moderate." (PMID 40149943, 2025). "Renal concentrations of TNF‐α, IL‐6, and IL‐1β were assessed in the Sham, sepsis and Cur + Sep groups." (PMID 41140036, 2025). "The increase in IL-6 levels was lower in the TCZ1 group compared to the sepsis group and other TCZ treatment groups." (PMID 39955435, 2025). "The key proinflammatory cytokines in sepsis, IL-6 and TNF-α, were both significantly higher in the blood of mice with CLP than in mice with sham operation." (PMID 41157235, 2025). "IL-6 with a large molecular weight can serve as the main factor for evaluating the prognosis of sepsis." (PMID 40281760, 2025). "We observed a myocardial upregulation in expression of inflammatory cytokines IL-1β and IL-6 along with increased macrophage staining, which was more pronounced in acute than in prolonged sepsis." (PMID 39821755, 2025). "A receiver operating characteristic (ROC) analysis was conducted using IL-6 concentrations at 24 h after CLP-sepsis induction and the outcome was assessed until 7 days." (PMID 40241761, 2025). "In our study, there are many IL-6 related signaling pathways that can induce sepsis, and the activation of these inflammatory signaling pathways is related to these factors cross-talking, therefore, our team has drawn a mechanism map." (PMID 39891057, 2025). "The IL-6 concentrations in the LPS mice reported here are within the range of the cutoff values for serum IL-6 which is used to diagnose human sepsis." (PMID 40411815, 2025). "Based on the ROC analysis, a cut-off value of 808 pg/mL was identified and IL-6 demonstrated a sensitivity of 63% and a specificity of 62% for sepsis prediction (p = 0.44)." (PMID 41011807, 2025). "The value of IL-6 in immunocompromised patients with sepsis has been studied to some degree, with recent research mainly focused on the pediatric population." (PMID 40142279, 2025). "In this ICU cohort, IL-6 concentrations were markedly elevated in patients with sepsis and in those with neutropenia, with the highest levels observed in individuals affected by both." (PMID 41155261, 2025). "Another notable difference is that our study demonstrates a positive correlation between serum IL-34 levels and IL-6, PCT, and lactate levels during the onset of sepsis patients, which is also associated with prognosis." (PMID 40176879, 2025). "In the ELISA, CBD treatment indicated the downregulation of TNF-α, IL-6, and IL-1β expression levels in the serum samples of the LPS-mediated sepsis mouse models." (PMID 41465451, 2025). "These children with malignancy were immunosuppressed, particularly the adaptive immune system; therefore, innate immunity, such as monocytes and macrophages, will over-activate and produce excessive IL-6 after sepsis." (PMID 40136690, 2025). "○Enhanced antibacterial and antibiofilm activity against Gram‐positive and negative bacteria.○Reduction in the levels of TNF‐α, IL‐1β and IL‐6 in CLP model.○Effective reduction of sepsis‐induced multiple organ damage.○Improved survival rates." (PMID 40599085, 2025). "Some of the anti-inflammatory mechanisms of this molecule in sepsis include reducing IL-6 and inducible nitric oxide synthase (iNOS)." (PMID 41357527, 2025). "For example, monoclonal antibodies against IL-6 or its receptor, such as tocilizumab, have shown efficacy in dampening the cytokine storm in sepsis and are also being explored as treatments for certain cancers." (PMID 40563999, 2025). "IL-17 (also known as IL-17A) is produced by IL-23-stimulated Th17 T cells after sepsis and induces the synthesis of various cytokines such as IL-1β, IL-6, and TNF-α." (PMID 40520010, 2025). "For this reason, in the initial phase of our study, alterations in 24-h serum IL-6 levels, lung injury, and kidney injury, as well as their interrelationships, were assessed in rats with LPS-induced sepsis." (PMID 39955435, 2025).
Sepsis (continued). "In the future, it will be necessary to examine the differences in adsorption effects for each substance using test solutions that include a variety of substances involved in sepsis, in addition to IL-6." (PMID 39958120, 2025). "In sepsis, the early surge of interleukin-6 favors Th17 expansion, while in later stages the predominance of T regulatory cells contributes to immune paralysis." (PMID 41268545, 2025). "Given that elevated IL-6 levels indicate a significant inflammatory burden in sepsis, the study demonstrated that TCZ application during the cytokine storm period, characterized by hyperinflammation, is less effective." (PMID 39955435, 2025). "The determination of IL-6 from umbilical cord blood has a sensitivity of over 87% for early-onset sepsis." (PMID 40149646, 2025). "Systemic inflammatory response syndrome triggered by sepsis ramps up the production of inflammatory signaling molecules like IL-6 and TNF-α, while simultaneously kicking the coagulation system into overdrive." (PMID 40959822, 2025). "The innate and adaptive immune systems release inflammatory cytokines early in sepsis to eliminate foreign pathogens, such as IL-6, TNF-α, and IL-1β." (PMID 40718494, 2025). "This expanded scope offers a more comprehensive assessment of IL-6’s potential role as a prognostic biomarker in sepsis." (PMID 40149943, 2025). "During sepsis, exosomes contribute to the progression of inflammation by carrying proinflammatory cytokines (such as IL-1β, IL-6, TNF-α) and activating Toll-like receptors (TLR2, TLR4, TLR7) in immune cells." (PMID 41268545, 2025). "In sepsis models and clinical observations, metformin reduces macrophage TNF-α and IL-6 secretion and alleviates immunosuppression‐associated dysfunction, highlighting its potential in acute inflammation regulation." (PMID 40584964, 2025). "STAT3, a principal transcription factor downstream of the IL-6 signaling pathway, plays a vital role in the early stages of sepsis." (PMID 39877839, 2025). "At the 16th hour, all sepsis groups (G3–G7) demonstrated a highly significant increase in serum IL-6 levels compared to the control group (G1) (p < 0.01)." (PMID 41517447, 2025). "In intensive care, IL-6 is used to monitor critically ill patients, particularly for early sepsis detection." (PMID 40310334, 2025). "Nevertheless, one major clinical limitation for the use of UC IL-6 as a predictor for sepsis is the variable cut-off values reported in the studies." (PMID 41302151, 2025). "By activating the IL-6 related signaling pathway, some chronic diseases are prone to sepsis via stimulated by chronic low-grade inflammation, meanwhile, sepsis can exacerbate these chronic diseases and lead to MOF." (PMID 39891057, 2025). "Sepsis triggers increased C3, IL-6 and TNF-α in spinal astrocytes, while administration of the α2A-adrenergic receptor (α2-AR) agonist dexmedetomidine blocked inflammatory factor production, neuronal damage, and cardiac dysfunction." (PMID 40692211, 2025). "ELISA was used to measure systemic inflammatory responses in sepsis model rats by determining concentrations of serum IL-6, IL-1β and TNF-α." (PMID 40582762, 2025). "IL-6 levels were significantly increased in the sepsis group and all TCZ-treated groups relative to the healthy group." (PMID 39955435, 2025). "One large-scale study found that patients with severe sepsis secondary to pneumonia had a significant increase in IL-6 and IL-10 levels one day after the onset of sepsis, with males showing higher levels compared to females." (PMID 40362448, 2025). "This variation stems from a multitude of factors related to the patient populations of our included studies: the severity of sepsis, IL-6 measurement techniques, and statistical methodologies." (PMID 40149943, 2025).
Sepsis (continued). "The LR-based model integrating RDW, APACHE II score, and biomarkers (PCT, IL-6, CRP, cystatin C) effectively predicts the risk of AKI in children with sepsis, offering a valuable tool for early intervention and improved patient outcomes." (PMID 41281283, 2025). "The initiation of NF-κB activation is controlled by the phosphorylation of IκB-α, leading to its degradation and, consequently, upregulation of inflammatory cytokines, including TNF-α, IL-1β, and IL-6, which are considered hallmarks of sepsis." (PMID 39940359, 2025). "In sepsis-associated AKI, elevated IL-6 levels correlate strongly with the deterioration of renal function." (PMID 41488110, 2025). "Toxins generated in the host during the progression of sepsis activate macrophages, leading to the release of various inflammatory cytokines such as IL-1, IL-6, IL-8, and tumor necrosis factor-alpha (TNF-α), mediated through MAPK and NF-κB pathways." (PMID 41517447, 2025). "A 20 pg/mL IL-6 threshold achieved 100% sensitivity, capturing all sepsis cases (15/15) and fatalities (6/6)." (PMID 40647525, 2025). "Moving forward, research should prioritize addressing the limitations identified in this review and exploring new avenues for understanding the role of IL-6 in sepsis prognosis." (PMID 40149943, 2025). "IL-6 is a multifunctional cytokine, and studies have shown that elevated levels of IL-6 are indicators of sepsis progression and prognosis in patients with severe infections." (PMID 40072101, 2025). "The combination of these tests increased the diagnostic accuracy of the combination of the WBC count and CRP level, proving useful in the diagnosis of sepsis and comparable to the use of IL-6 and TNF-α." (PMID 40806505, 2025). "CLU levels tend to decrease in patients with severe sepsis and qSOFA ≥2 and correlated inversely with pro‐inflammatory cytokines (IL‐6, TNFα) and inflammatory markers (CRP)." (PMID 40722110, 2025). "IL-6 is widely recognized as a promising biomarker for sepsis due to its strong correlation with sepsis severity." (PMID 40178612, 2025). "It was reported that NF-κB is activated with TLR-4 and promotes the level of TNF-α, IL-16, and IL-6 in the tissue of sepsis rats." (PMID 41221897, 2025). "Together, this suggests that the marked increase and loss of circadian rhythm in circulating glucocorticoids and the increase in IL-6 likely drive the increase in leptin levels in early sepsis." (PMID 39968295, 2025). "This surge in IL-6 plasma values, coupled with its early appearance in the course of the disease, reflects its utility as a biomarker for sepsis." (PMID 40149943, 2025). "Another study showed that cardiac tissue TNF-α and IL-6 levels were significantly lower in the ghrelin-treated group compared to the sepsis model group." (PMID 39144689, 2024). "Secondary goals encompass assessing the occurrence of sepsis, osteopenia, hyperparathyroidism, and interleukin-6 concentration." (PMID 38474827, 2024). "The PERiPLEX® system utilizes a lateral flow assay to MMP-8 and IL-6, utilizing peritoneal dialysate derived from a dialysis effluent as significant inflammatory indicators with high concentrations during sepsis cases." (PMID 38893639, 2024). "Significantly elevated levels of pro-inflammatory cytokines, including TNFα, IL-1, and IL-6, have been observed in endotoxemia/sepsis in males compared to females." (PMID 39684541, 2024). "Like inflammation due to sterile lung injury and repetitive LPS injections, peripherally induced inflammation in our rat model of sepsis triggered an increase in the concentration of the proinflammatory cytokines IL-1β, IL-6 and IL-17 in the brainstem." (PMID 38331902, 2024). "In contrast, IL-6 is one of the earliest biomarkers in sepsis, increasing very soon after infection and peaking at around 2 h." (PMID 38240873, 2024). "In HIV patients, elevated cytokine levels of interleukin (IL)-1, IL-6, IL-10, and tumor necrosis factor (TNF) are associated with the pathogenesis of sepsis in acute cases." (PMID 39676169, 2024).
Sepsis (continued). "We found that Il-6 blockade with tocilizumab is a potential therapeutic strategy for severe sepsis/septic shock in seven children with febrile neutropenia." (PMID 38672594, 2024). "A retrospective study found that when patients had high levels of CRP, PCT, and IL-6, their sepsis mortality rate was relatively higher." (PMID 38947447, 2024). "An elevated concentration of circulating IL-6 is an established indicator of an activated inflammatory process and a predictor of unfavorable symptoms and deaths in animal and human sepsis." (PMID 39281680, 2024). "IL-6 is a kind of glycoprotein produced by lymphocytes and macrophages; a healthy level is 15 pg mL−1, increasing to over 3 ng mL−1 for a sepsis patient." (PMID 38920613, 2024). "Similar findings were observed in our study, indicating that patients with significantly elevated serum IL-6 and IL-10 concentrations at an early stage have the ability to predict progression to sepsis and ICU admissions." (PMID 39212218, 2024). "IL-6-deficient mice are more susceptible to invasive candidiasis than wild type mice, which suggests that IL-6 release is fundamental during fungal infection and the severity of sepsis." (PMID 38787374, 2024). "Of note, the IL-6 levels in these mice were considerably lower than those reported during acute sepsis." (PMID 39015379, 2024). "IL-6 levels have been shown to be significantly elevated up to 48 h prior to clinical signs of sepsis." (PMID 38671704, 2024). "Numerous studies have demonstrated that sepsis patients exhibit altered cytokine responses, including reduced production of tumor necrosis factor, interleukin-1 (IL-1), interleukin-6 (IL-6), and lymphocyte apoptosis." (PMID 39655195, 2024). "Unsurprisingly, the levels of IL-1β, TNF-α, and IL-6 produced by TREM2+ monocytes were positively correlated with serum triglyceride concentrations of sepsis patients." (PMID 39405126, 2024). "Clinical trials of anti–IL-6 and reanalysis of IL-1RA for sepsis have yielded insights into the importance of these pathways in the host inflammatory response to pathogens in specific subsets of patients." (PMID 39666381, 2024). "IL-6 is a key mediator of the inflammatory response and is often elevated in sepsis, reflecting the extent of cytokine activation." (PMID 38474222, 2024). "Interleukin-6 (IL-6)is known to play a critical role in the progressionof inflammatory diseases such as cardiovascular disease, cancer, sepsis,viral infection, neurological disease, and autoimmune diseases." (PMID 38745465, 2024). "Studies have demonstrated that inflammatory markers such as CRP, PCT, and IL-6 are commonly utilized indicators to reflect the degree of inflammatory response in sepsis and predict disease severity." (PMID 38947447, 2024). "Inadequate sample storage can also affect the stability of sepsis biomarkers (e.g., IL-6), which can significantly interfere with appropriate diagnosis." (PMID 38920613, 2024). "We also showed that irisin was negatively associated with most inflammatory biomarkers (CRP, procalcitonin, IL-6, IL-10) at sepsis onset, in accordance with in vitro studies." (PMID 38540711, 2024). "Divergent results have been published for neonates with early onset sepsis, ranging from decreased IL-6 production in term neonates, which is even more prominent in preterm infants, to IL-6 values similar to those observed in adults." (PMID 38535886, 2024). "Sepsis is associated with high levels of inflammatory cytokines such as TNF-α, IL-1β, IL-6, and IL-10." (PMID 39597952, 2024). "In healthy individuals, IL-6 levels fall between 1 pg/mL to 25 pg/mL; however, levels rise above 1 ng/mL during sepsis." (PMID 39769181, 2024). "To conclude, our data suggest that HNF4α dysfunction in sepsis prevents an adequate APR towards IL6, potentially compromising liver regeneration and the removal of hemoglobin and heme during hemolysis." (PMID 39261648, 2024).
Sepsis (continued). "Further analysis through 16S sequencing of RBC-bound DNA illustrated distinct microbial communities, with RBC-bound DNA composition correlating with plasma IL-6 in patients with sepsis." (PMID 38746470, 2024). "In horses, the production of IL-6 also occurs in response to infection, has been shown to be significantly elevated in cases of sepsis or severe SIRS, and has been correlated with disease severity and outcome." (PMID 39273060, 2024). "For example, increases in IL-6 and IFN-γ levels are associated with sepsis and wound disruption, while the IL-10 concentration can be used to determine the occurrence of postoperative complications such as atrial fibrillation." (PMID 38704573, 2024). "Pre-administration of IL6 and dexamethasone, which maximally activate the acute phase response, protects against sepsis." (PMID 39261648, 2024). "Meloxicam-treated sepsis mice in high IL-6 responders had increased liver IL-1β levels compared to Metamizole-treated ones (2.25-fold, adj.P=0.030)." (PMID 39281680, 2024). "The levels of IL-1β and IL-6 appear to correlate with the severity of sepsis, as they are found at higher levels in deceased patients compared to survivors." (PMID 39063011, 2024). "In sepsis, systemic inflammation marked by elevated cytokines like IL-6 and TNF-α impairs erythropoiesis, leading to increased RDW, which correlates with disease severity and poor outcomes." (PMID 39844844, 2024). "Initial phases of sepsis are punctuated by a hyper-inflammatory surge, marked by a deluge of inflammatory cytokines like IL-1, IL-6, and notably, TNF-α42." (PMID 38326366, 2024). "The relationship between IL-6 and MIP proteins seems intrinsically linked; in vivo, MIP-1α (and beta) has been shown to correlate with levels of IL-6 in sepsis." (PMID 38672079, 2024). "Blocking SEMA3A in sepsis led to a decreased secretion of TNF-α and IL-6, which was associated with lower mice mortality." (PMID 39770766, 2024). "We proved that Fen and Melo significantly alleviated severe inflammation and reduced TNF-α, IL-1β, and IL-6 production in LPS-induced sepsis models, thus warranting further exploration of their role in sepsis clinical treatment." (PMID 39628572, 2024). "Sepsis causes immune cells to release cytokines such TNF-α, IL-1, and IL-6, resulting in systemic inflammation." (PMID 39735547, 2024). "While TNF-α and IL-1 drive the initial responses during the early stages of sepsis, the blood levels of IL-6 can be maintained over a longer period." (PMID 39056754, 2024). "The early stages of sepsis are characterized by a state of hyperinflammation, driven by the systemic production of inflammatory cytokines, such as IL-1, IL-6, and TNF-α." (PMID 38546748, 2024). "In vivo, RGD-lipo/Cur significantly reduced the release of inflammatory cytokines (TNF-α and IL-6) and prevented sepsis-induced organ damage in the LPS-induced mice sepsis model." (PMID 38637839, 2024). "Overall, sepsis strongly enhanced the IL-6 (> eightfold), TNFα (> 32-fold) and IL-1β (25-fold) gene expression." (PMID 39497013, 2024). "Evidence from preclinical studies supports the therapeutic potential of IL-6 blockade, showing that antibodies targeting IL-6 can improve survival and physiological responses in sepsis models." (PMID 39056754, 2024). "Our study demonstrated a significant correlation between sTREM-1 levels and other commonly used sepsis biomarkers, including IL-6, lactate, PCT, and CRP." (PMID 39655134, 2024). "The exacerbation of sepsis, resulting in consequences such as multiple organ failure, is attributed to the detrimental effects of inflammatory cytokines, including IL-6 and TNF-α." (PMID 38629103, 2024). "Future studies to decipher the mechanisms that can lead to an exuberant production of TNF-α and IL-6 and to better understand the detrimental inflammatory response in those newborns that progress to sepsis during a bacterial infection are essential." (PMID 38562936, 2024).